TBC1D1 (TBC1 domain family member 1)
Diseases named in the same sentence as TBC1D1 in open-access papers (continued):
Sharing a sentence is not in itself a finding about the gene and the disease.
Hyperglycemia (2 papers, 2019 to 2023). An increased concentration of glucose in the blood. "Benzyl isothiocyanate enhances Nrf2-dependent antioxidant defense, mediates skeletal muscle IRS-1/AKT/TBC1D1 signalling, and improves GLUT4 expression, thereby ameliorating high-fat diet-induced hyperglycemia." (PMID 37779908, 2023).
Myocardial infarct (2 papers, 2015 to 2021). "Myocardial infarct induces the expression of Tbc1d1 in murine heart muscle both in infarct zone and border zone." (PMID 33769190, 2021). "Interestingly, myocardial infarction induced the expression of a related RabGAP, TBC1D1, in the infarct zone as well as in the border zone." (PMID 25923736, 2015).
acute lymphoblastic leukemia (1 paper, 2017). Leukemia with an acute onset, characterized by the presence of lymphoblasts in the bone marrow and the peripheral blood. "TBC1D1 has been reported to have a potential downstream role of silencing of pre-BCR signaling in acute lymphoblastic leukemia in human." (PMID 29375555, 2017).
astrocytomas (1 paper, 2024). "Remarkably, varying levels of TBC1D1 were observed in different histological types, with higher expression in astrocytomas compared to oligoastrocytomas or oligodendrogliomas." (PMID 38529286, 2024).
atopic dermatitis (1 paper, 2023). "Recently, it has been reported that TBC1D1 is potentially associated with the etiology of atopic dermatitis in dogs, a chronic inflammatory and pruritic skin disease." (PMID 36902003, 2023).
autoimmune thyroid disease (1 paper, 2024). Inflammatory disease of the thyroid gland due to autoimmune responses leading to lymphocytic infiltration of the gland. "Our GSEA analysis revealed strong evidence of a significant correlation between elevated expression of TBC1D1 and pathways related to type I diabetes mellitus, complement and coagulation cascades, allograft rejection, autoimmune thyroid disease, and graft versus host disease signaling." (PMID 38529286, 2024).
cardiac hypertrophy (1 paper, 2022). "In murine skeletal muscle, TBC1D1 appears to control exercise endurance, and its ablation is associated with high-fat diet-induced diastolic dysfunction, left ventricular fibrosis and cardiac hypertrophy." (PMID 36139463, 2022).
Crohn disease (1 paper, 2021). A gastrointestinal disorder characterized by chronic inflammation involving all layers of the intestinal wall, noncaseating granulomas affecting the intestinal wall and regional lymph nodes, and transmural fibrosis. "CDKN2AIP is critical for the DNA damage response and TBC1D1 has been linked to Crohn’s disease, and lymphocyte count." (PMID 33563976, 2021).
depression (1 paper, 2023). "After identification and validation, CLDN5 and TBC1D1 were regarded as the hub genetic links of ED and depression." (PMID 38111702, 2023). "It was validated and determined that CLDN5 and TBC1D1 were the hubs of genetic links between ED and depression." (PMID 38111702, 2023). "Finally, CLDN5 and TBC1D1 were well-validated and identified as the hub crosslinks between ED and depression." (PMID 38111702, 2023). "Therefore, it is significant to explore the specific mechanisms of CLDN5 and TBC1D1 in the crosslink of ED and depression." (PMID 38111702, 2023). "In the available studies, TBC1D1 was not reported to be involved in the pathogenesis of ED or depression, but it is one of the suicide attempt polygenes that may have a link to depression." (PMID 38111702, 2023).
infarction (1 paper, 2015). A localised pathological necrosis of tissue resulting from obstruction of the blood supply usually by a thrombus, an embolus, or vascular torsion. "Nevertheless, these data demonstrate that TBC1D1 can be used as a novel biomarker to monitor cardiac remodeling during infarction." (PMID 25923736, 2015).
melanoma (1 paper, 2024). A malignant, usually aggressive tumor composed of atypical, neoplastic melanocytes. "Analysis of the TIGER database of patients receiving anti-PD-1 immunotherapy for melanoma revealed that TBC1D1 impedes the effectiveness of the treatment, leading to suboptimal patient survival rates." (PMID 38529286, 2024).
overnutrition (1 paper, 2022). An imbalanced nutritional status resulting from excessive intake of nutrients. "This study shows that overnutrition suppresses the phosphorylation of AMPK and TBC1D1, augmenting the level of GTP-bound Rab2A and increasing the stability of PPARγ, which ultimately promotes the hepatic accumulation of lipids." (PMID 35061665, 2022). "Overnutrition in the DIO mice expectedly inactivated AMPK as evidenced by decreased phosphorylation of AMPK, which consequently resulted in lower TBC1D1 phosphorylation in the liver." (PMID 35061665, 2022).
psoriasis (1 paper, 2022). An autoimmune condition characterized by red, well-delineated plaques with silvery scales that are usually on the extensor surfaces and scalp. "One selection signal in common type Labrador retriever cases positions across the TBC1D1 gene (body weight) and one signal of selection in working type German shepherd controls overlaps the LRP1B gene (brain), near the KYNU gene (psoriasis)." (PMID 36482174, 2022).
cancer (8 papers, 2012 to 2024). A tumor composed of atypical neoplastic, often pleomorphic cells that invade other tissues. "Expanding our inquiry, we induced the differentiation of bone marrow-derived monocytes into different subtypes of macrophages and examined the protein and mRNA levels of TBC1D1 in cancer-associated fibroblasts and splenic T cells." (PMID 38529286, 2024). "Despite its association with the progression and development of certain cancers, the precise biological functions and role of TBC1D1 in disease pathogenesis remain incompletely understood, underscoring the necessity for further research to identify it as a potential therapeutic target." (PMID 38529286, 2024). "The immunoprecipitation assay indicated that FZD7, which is universally upregulated in cancer, could associate with TBC1D1." (PMID 36371204, 2022). "eIF3a regulation of AMPK and glucose uptake in promoting cancer cell proliferation may work through TBC1D1 and TXNIP regulation of GLUT4 and GLUT1." (PMID 35595099, 2022). "Additionally, TBC1D1 has been identified as an important regulator in some cancers." (PMID 38529286, 2024). "The results showed that the mRNA levels of TBC1D1, TBC1D7, TBC1D8 and TBC1D14 significantly varied between different cancer stages, whereas the mRNA levels of TBC1D9b and TBC1D25 did not." (PMID 38766486, 2024). "Although there are not many studies on TBC1D1 in cancer, the present study identified the potential of TBC1D1 as a biomarker of HCC." (PMID 38766486, 2024).
tumor (6 papers, 2020 to 2024). "In this study, the analysis of the TIME database showed that TBC1D1 level was significantly associated with the infiltrating levels of TIICs and tumor immune invasion." (PMID 38766486, 2024). "Additionally, patients with high TBC1D1 expression exhibited increased infiltration of M2 tumor-associated macrophages (TAMs), showing significant elevation in markers including CD68 and ARG1." (PMID 38529286, 2024). "In conclusion, the results suggest a notable correlation between TBC1D1 expression and key clinical variables such as patient age, tumor grade, and histological type." (PMID 38529286, 2024). "Additionally, elevated TBC1D1 expression upregulates immune checkpoint molecules within tumor tissue, further contributing to immunotherapy resistance." (PMID 38529286, 2024). "Paired sample analysis also confirmed elevated TBC1D1 expression in tumor tissues." (PMID 38529286, 2024). "Our findings indicated that TBC1D1 was expressed in M2-like macrophages, akin to tumor cells." (PMID 38529286, 2024). "We further investigated the impact of TBC1D1 on treatment tolerance, focusing on its effect on the function of cytotoxic T lymphocytes (CTL), which play a crucial role in eliminating tumor cells." (PMID 38529286, 2024). "Tumor Immune Dysfunction and Exclusion (TIDE) database was utilized to assess T-cell function, while Tumor Immunotherapy Gene Expression Resource (TIGER) database was employed to evaluate immunotherapy resistance in relation to TBC1D1." (PMID 38529286, 2024). "We hypothesize that by targeting TBC1D1 in combination with ICB, the efficacy of antitumor immunotherapy can be enhanced, potentially inhibiting tumor progression and improving patient survival." (PMID 38529286, 2024). "Furthermore, TBC1D1 exhibited a positive correlation with macrophage infiltration and markers, while displaying a negative correlation with CD8+ T cells, an immune cell type renowned for its anti-tumor properties." (PMID 38529286, 2024). "Therefore, based on these findings, we hypothesize that high-TBC1D1 macrophages within the TME may promote an immunosuppressive state, impairing CD8+ T cell function and enabling tumor immune escape, ultimately propelling tumor progression." (PMID 38529286, 2024). "Our mechanistic study revealed that TBC1D1-mediated inhibition of CTL function could be attributed to the upregulation of various immune checkpoint molecules, including ARG1, CD68, PDCD1, CD274, TGFB1, and CTLA4, collectively impeding the anti-tumor immune response." (PMID 38529286, 2024).
TBC1D1 also shares sentences with these, for which no sentence is quoted: metabolic disease (2 papers); amyotrophic lateral sclerosis (1); celiac disease (1); cerebral palsy (1); erectile dysfunction (1); Hepatic steatosis (1); hepatoma (1); movement disorder (1); nonalcoholic fatty liver disease (1); oligoastrocytoma (1); oligodendroglioma (1); periodontal disease (1); renal agenesis (1); schizophrenia (1); skin cutaneous melanoma (1); type 1 diabetes mellitus (1).